HIF1A (hypoxia inducible factor 1 subunit alpha)
Diseases named in the same sentence as HIF1A in open-access papers (continued):
Sharing a sentence is not in itself a finding about the gene and the disease.
diabetic encephalopathy (1 paper, 2017). A brain disease that is characterized by functional impairment of cognition, cerebral signal conduction, neurotransmission and synaptic plasticity, and underlying structural pathology associated with diabetes. "Since hypoxia may mediate diabetic encephalopathy progression, we further detected HIF-1α level in the hippocampus." (PMID 29296174, 2017).
diabetic macular edema (1 paper, 2023). "Previously, Maugeri and co-workers provided evidence that PACAP is able to decrease and inhibit HIF1-α and VEGF-A expression in a diabetic macular edema model." (PMID 37686074, 2023).
diabetic neuropathy (1 paper, 2018). A chronic, pathological complication associated with diabetes mellitus, where nerve damages are incurred due to diabetic microvascular injury involving small blood vessels that supply these nerves, resulting in peripheral and/or autonomic nerve dysfunction. "This study demonstrated the three key molecular signatures of microangiopathy-mediated diabetic neuropathy downstream of CD40: HIF-1α, MK2 and PTEN." (PMID 29549140, 2018). "We chose to investigate the relationship between HIF-1α, MK2 and PTEN, and CD40 as they were upregulated in the endothelial cells of sural nerve microvasculatures and were all major determinants of microangiopathy and nerve morphometry in diabetic neuropathy." (PMID 29549140, 2018).
dissection (1 paper, 2023). The separation and isolation of tissues for surgical purposes, or for the analysis or study of their structures. "HIF-1α activation also promotes the progression of aortic dissection through vascular inflammation, extracellular matrix degradation, and rupture of the elastic fibers." (PMID 37283588, 2023).
distal colitis (1 paper, 2015). Particular variety of ulcerative colitis where only the left half of the colon is inflamed. "Thus, the aim of the present study was to investigate the therapeutic effects of HBO on experimentally induced acute distal colitis focusing on its effect on the production of pro-inflammatory cytokines, nitric oxide synthase and HIF-1α." (PMID 25926972, 2015).
duodenal adenocarcinoma (1 paper, 2025). A carcinoma that arises from glandular epithelial cells of the duodenum. "The HIF1α, STAT3, and MYC expression levels in duodenal adenocarcinoma were analyzed alongside their correlation with Linc01559." (PMID 40722682, 2025).
duodenal neuroendocrine tumor (1 paper, 2024). "Ten patients were enrolled; two showed reductions in HIF-1α protein and mRNA levels, and one patient with a duodenal neuroendocrine tumor had prolonged stabilization of disease." (PMID 38396737, 2024).
Enterobacteriaceae Infections (1 paper, 2023). Infections with bacteria of the family ENTEROBACTERIACEAE. "Conversely, previous research has demonstrated that Enterobacteriaceae infection can also activate HIF-1 and alter epithelial cells, despite the fact that HIF1-α does not affect proinflammatory gene expression in IEC." (PMID 37875985, 2023).
enteropathy (1 paper, 2019). "The next study with IELs populations in mice by using flow cytometry confirmed the importance of IECs-derived Hif1-α in the development of NSAID-induced enteropathy." (PMID 31040849, 2019). "Because NSAIDs mainly causes damage to the small intestine, we investigated the effects of epithelial Hif-1α knockout in NSAIDs-induced small intestinal injury (enteropathy)." (PMID 31040849, 2019).
erectile dysfunction (1 paper, 2025). Persistent or recurrent inability to achieve or to maintain an erection during sexual activity. "It is notable that recent studies have also found that Rg5 can inhibit the increase in Hif-1α level caused by hypoxia, showing therapeutic potential for erectile dysfunction." (PMID 40514732, 2025).
esophageal reflux (1 paper, 2025). "In addition, studies in patients with alterations in esophageal reflux have demonstrated a significant role for the stabilization of hypoxia-inducible factor subunits (HIF-1α and HIF-2α)." (PMID 41156042, 2025).
esophageal tumors (1 paper, 2012).
fallopian tube cancer (1 paper, 2014). A primary or metastatic malignant neoplasm that affects the fallopian tube. "The small number of patients precluded statistical correlation with response, but two of the four patients with a decrease of HIF-1α expression experienced a decrease in tumor size (19% and 15% decrease in prostate and fallopian tube cancers, respectively)." (PMID 25373733, 2014).
Fanconi anemia (1 paper, 2022). Fanconi anemia (FA) is a hereditary DNA repair disorder characterized by progressive pancytopenia with bone marrow failure, variable congenital malformations and predisposition to develop hematological or solid tumors. "The Fanconi anemia pathway is activated by hypoxic stress, which aligns with the upregulation of markers of hypoxic stress (eg, significant increase in the hypoxia-inducible factor-alpha [Hif1-a] gene in the crypt at high concentrations, and in the villus at nearly all concentrations of Cr(VI)." (PMID 34935971, 2022).
fibrodysplasia ossificans progressiva (1 paper, 2021). Fibrodysplasia ossificans progressiva (FOP) is a severely disabling heritable disorder of connective tissue characterized by congenital malformations of the great toes and progressive heterotopic ossification that forms qualitatively normal bone in characteristic extraskeletal sites. "A recent study investigated the role of hypoxia and hypoxia-inducible factor 1α (HIF-1α) in fibrodysplasia ossificans progressiva (FOP)." (PMID 34163523, 2021).
fungal keratitis (1 paper, 2017). "The average ratios of the expression levels of the Hmox1, Nos3, Hif1a, Sod2, Sod3, and Gpx2 genes increased more than 2-fold (p < 0.05) at day 1 p.i. in the fungal keratitis model, whereas the expression ratios of the Hif1an and Prdx6 genes decreased more than 2-fold (p < 0.05)." (PMID 28874754, 2017).
germinal matrix hemorrhage (1 paper, 2021). "In brain specimens obtained from 12 premature infants (7 with histopathological evidence of germinal matrix hemorrhage), the most prominent expression of HIF1α was noted in infants with frank germinal matrix hemorrhage." (PMID 34769328, 2021).
glycogen storage disease type Ib (1 paper, 2019). "PPARγ upregulation has previously been linked to changes in neutrophil function in patients with glycogen storage disease type Ib, where circulating neutropenia and defective respiratory burst are described, alongside increased levels of HIF-1α." (PMID 30849228, 2019).
H1N1 virus infection (1 paper, 2025). "Research has shown a role for HIF-1α in the regulation of pro-inflammatory factors during the inflammatory response and promotes viral replication in H1N1 virus infection." (PMID 40872344, 2025).
hair follicle tumours (1 paper, 2014). "The expression levels and staining intensity of BNIP3, CAIX, GLUT1, Hif1α, pAKT, PHD2, pmTOR, pS6 and VEGF-A in hair follicle tumours." (PMID 25181405, 2014).
heart injury (1 paper, 2024). Injury to the heart. "This indicates that myeloid Hif1α may play a role in the reperfusion component of ischemic heart injury." (PMID 39433910, 2024). "Hif1α deletion in resident macrophages arrested progression through this differentiation trajectory, and proper progression of this trajectory was protective in the context of ischemic heart injury." (PMID 39433910, 2024).
hemangioendothelioma (1 paper, 2020). A vascular proliferation characterized by the presence of prominent endothelial cells and the formation of vascular channels. "In hemangioendothelioma cells, ART time- and dose-dependently reduced tumor cell growth, concomitantly decreasing the expression of VEGF-A, VEGFR1, VEGFR2, and HIF-1α." (PMID 33121039, 2020).
hemarthrosis (1 paper, 2016). Bleeding into the joints. "We had previously established that in the multiple injury model of hemarthrosis (Day 30/60/75/90), factors that contribute to hypoxia (HIF-1α, 3.3–6.5-fold), angiogenesis (VEGF-α, 2.5–4.4-fold) and chondrocyte damage (matrix metalloproteinase 13 (MMP13), 2.8–3.8-fold) were significantly elevated." (PMID 27070581, 2016).
Hematochezia (1 paper, 2024). The passage of fresh (red) blood per anus, usually in or with stools. "Surprisingly, HIF-1α KO mice exhibited a transiently enhanced disease activity that comprises weight loss, stool consistency, and hematochezia during the third DSS challenge and a worsened histological score at the endpoint, despite a decrease in ILC1 frequencies." (PMID 38876796, 2024).
hepatobiliary tumors (1 paper, 2017). "Chronic alcohol abuse accelerates hepatobiliary tumors by upregulating miR-122-mediated HIF-1α activity and stemness." (PMID 28426730, 2017).
hereditary hemorrhagic telangiectasia (1 paper, 2023). A disorder of angiogenesis leading to arteriovenous dilatations: cutaneo-mucosal hemorrhagic telangiectasias and visceral shunting. "In hereditary hemorrhagic telangiectasia (HHT), we have previously observed that impairment of the TGF-β pathway is associated with downregulation of HIF-1α." (PMID 37629565, 2023).
histoplasmosis (1 paper, 2019). A disease caused by the fungus Histoplasma capsulatum. "Myeloid HIF-1α is essential for promoting antifungal immunity in a mouse model of histoplasmosis by tempering immunosuppressive interleukin-10 (IL-10)." (PMID 31036602, 2019). "Previously, we revealed a fundamental role of myeloid HIF-1α in controlling histoplasmosis by dampening the capacity of IL-10 to inhibit intracellular growth of H. capsulatum." (PMID 31036602, 2019).
hydronephrosis (1 paper, 2016). Collection of urine in the renal pelvis that results in dilatation of the renal pelvis and calyces. "The hydronephrosis, polyuria and polydipsia phenotypes were completely rescued by co-deletion of Hif1a but not Hif2a, demonstrating that constitutive stabilization of HIF-1α in renal tubular cells is the cause of these phenotypes." (PMID 27528422, 2016).
Hypercalcemia (1 paper, 2022). An abnormally increased calcium concentration in the blood. "Data obtained in our study demonstrated that silencing of Drp1 exerted inhibitory properties in mitochondrial fragmentation to attenuate hypercalcemia-induced neurological impairment in CKD through the inactivation of ROS/HIF-1α/EZH2 axis." (PMID 36050772, 2022). "At last, CKD mice were injected with the corresponding AAV (sh-NC + Vector, sh-Drp1 + Vector, and sh-Drp1 + EZH2) to explore whether Drp1 could regulate the ROS/HIF-1α/EZH2 axis to alleviate neurological impairment induced by hypercalcemia in CKD." (PMID 36050772, 2022). "However, the interactions among Drp1, ROS, HIF-1α, EZH2, as well as their involvement in mitochondrial fragmentation and hypercalcemia-induced neuronal injury in the progression of CKD need to be explored more deeply." (PMID 36050772, 2022).
hyperphosphatemia (1 paper, 2023). Abnormally high level of phosphate in the blood. "Therefore, hyperphosphatemia may promote VC not only through activation of HIF-1α at the genetic level via Nrf2 but also through stabilization of HIF-1α at the protein level." (PMID 38102596, 2023).
hyperplasia (1 paper, 2014). An abnormal increase in the number of cells in an organ or a tissue with consequent enlargement. "The hypoxia-inducible factor-1α (HIF-1α) signaling pathway promotes the process of angiogenesis, contributing to the growth and progression of a number of hyperplasia diseases, including BPH." (PMID 24944609, 2014).
hyperprolactinaemia (1 paper, 2024). "Although (following the Rotterdam criteria) hyperprolactinaemia (HPRL) is an exclusion criterion for PCOS diagnosis, in our interactome, HIF1A has been included in the prolactin pathway." (PMID 39457593, 2024).
idiopathic osteonecrosis of the femoral head (1 paper, 2014). Most common form of osteonecrosis, the death of bone tissue following microvascular injury. "In a previous study, the HIF1α polymorphism at +45319C>T (the 1772C>T in our study) and several other loci are associated with idiopathic osteonecrosis of the femoral head (ONFH) in Korean men, suggesting that HIF1α variations play a role in the pathogenesis of ONFH." (PMID 25401740, 2014).
IgA nephropathy (1 paper, 2012). "HIF-1α was also detected in fibrotic areas of renal tissues from patients with IgA nephropathy." (PMID 23259746, 2012).
immune thrombocytopenia (1 paper, 2024). "In parallel, reduced expression of HIF-1α may lead to impaired megakaryopoiesis in mouse bone marrow cells treated with immune thrombocytopenia (ITP) plasma." (PMID 38902986, 2024).
infectious mononucleosis (1 paper, 2023). A condition characterized by an increase in mononuclear white blood cells and swollen lymph nodes, which is usually caused by infection with the Epstein-Barr virus. "However, the role of the AREG/EGFR/HIF-1α pathway in regulating interleukin-9 (IL-9) production by T cells in adult patients with infectious mononucleosis (IM) has not been fully elucidated." (PMID 36154925, 2023).
intestinal type adenocarcinoma (1 paper, 2007). An adenocarcinoma arising from epithelium which has undergone intestinal metaplasia. "The majority of intestinal-type adenocarcinoma specimens showed nuclear staining expression, with half staining strongly for HIF-1α." (PMID 17179985, 2007).
intracranial hypertension (1 paper, 2022). A finding characterized by increased cerebrospinal fluid pressure within the skull. "In the present study, we demonstrated that the upregulation of AQP4 and HIF-1α contributes to brain edema formation, a critical process involved in intracranial hypertension and cerebral hernia following traumatic brain injury (TBI)." (PMID 35177771, 2022).
iron metabolism disorders (1 paper, 2024). "For example, inhibiting HIF-1α diminishes the protective effect of DFO, which plays a crucial role in managing iron metabolism disorders and has a protective effect against neurological damage caused by ischemia and hypoxia." (PMID 39086755, 2024).
iron overload disease (1 paper, 2020). "DFO, which is clinically used as an iron chelator for treatment of patients with iron overload disease, inhibits the activity of prolyl hydroxylase, suppresses the transcriptional activity of HIF-1α and stabilizes HIF-1α." (PMID 32367141, 2020).
ischemic colitis (1 paper, 2020). Inflammation of the colon due to colonic ischemia resulting from alterations in systemic circulation or local vasculature. "Two ischemic factors, VEGF and hypoxia-inducible factor-1α (HIF-1α), were constitutively expressed in the human colon tissue and overexpressed in the ischemic colitis lesion." (PMID 32149087, 2020).
Kawasaki disease (1 paper, 2025). A rare inflammatory disease characterized by an acute febrile, systemic, self-limiting, medium-vessel vasculitis primarily affecting children. "PBMCs from patients with Kawasaki disease expressed higher levels of VEGFA and HIF-1α than did PBMCs from healthy control patients after 24 hours of incubation with NETs from patients with Kawasaki disease." (PMID 40083688, 2025).
keratoconus (1 paper, 2021). A degenerative, structural disorder of the eye, characterized by a cone-shaped protrusion of the cornea. "In this study, we investigated NF-κB, iNOS, HIF-1α, and HIF-2α as well as PHD2 expression, ROS production, and proliferation rate under hypoxic conditions in keratoconus corneal fibroblasts in vitro." (PMID 32886165, 2021). "In this study, we investigated the regulation of NF-κB, iNOS, HIF-1α, HIF-2α, and PHD expression; ROS, and proliferation under hypoxic conditions in keratoconus corneal fibroblasts compared with normal control cells, in vitro." (PMID 32886165, 2021).
Klebsiella pneumonia (1 paper, 2021). An pneumonia caused by infection with Klebsiella. "Mrp8-cre × Hif1αfl/fl mice showed an unaltered antibacterial defense, arguing against a role for HIF1α in neutrophils during Klebsiella pneumonia." (PMID 34393650, 2021). "To obtain insight into the role of macrophage HIF1α in the induction and perpetuation of lung inflammation during Klebsiella pneumonia, we determined the extent of lung pathology, neutrophil influx, and pulmonary cytokine levels." (PMID 34393650, 2021). "Of note, respiratory epithelial HIF1α has been shown to limit bacterial dissemination to the spleen during Klebsiella pneumonia, while it was not required for the induction of cytokines and chemokines in the airways." (PMID 34393650, 2021).
legionellosis (1 paper, 2022). Any disease caused by Legionella bacteria. "KEGG analysis showed that these molecules were mainly involved in ribosome, RNA transport, Spliceosome, HIF-1α signaling pathway and Legionellosis." (PMID 35757728, 2022).
lentivirus infection (1 paper, 2022). Virus diseases caused by the Lentivirus genus. "We then detected the changes of HIF-1α mRNA after lentivirus transfection and found that lentivirus infection caused significant changes in HIF-1α mRNA." (PMID 35664561, 2022). "Western blot confirmed that HIF-1α expression was successfully altered after lentivirus infection." (PMID 35664561, 2022).
leprosy (1 paper, 2020). Leprosy is a chronic infectious disease affecting primarily the skin and peripheral nervous system. "They found that a rare missense variant in HIF1A [MIM: 603348] and a common missense variant in LACC1 [MIM: 613409] contribute to leprosy susceptibility in Han Chinese." (PMID 33362202, 2020).
lip carcinomas (1 paper, 2023). A primary or metastatic malignant neoplasm involving the lip. "High HIF1α expression was noted in 30/60 lip carcinomas, and was significantly linked with low TIL density in the invading tumor front (p = 0.02)." (PMID 36900270, 2023).
liposarcoma (1 paper, 2013). A usually painless malignant tumor that arises from adipose tissue. "Several lines of evidence suggest HIF1α involvement in the progression of liposarcoma to a dedifferentiated state." (PMID 24216979, 2013).
liver hemangioma (1 paper, 2016). A hemangioma arising from the liver. "However, kidney hyperplasia and tubule defects were rescued by inactivation of Hif-1α, but not Hif-2α, whereas other kidney-specific Vhlh knockout mouse models did not develop liver hemangioma." (PMID 27733136, 2016).
lobular carcinomas (1 paper, 2002).
lung adenoma (1 paper, 2019). A benign, well circumscribed epithelial neoplasm that arises from the bronchus or the lung parenchyma. "Indeed as shown by either quantitative immunblotting or immunofluorescence (IF) analysis, each of 6 independent IKKαKO large lung adenomas have significantly enhanced HIF-1α protein levels." (PMID 31792060, 2019).
lung NET (1 paper, 2022). "The second aim of our study was the evaluation of hypoxia, through the IHC determination of HIF-1α expression, in the tumoural samples of lung NET patients." (PMID 36233825, 2022).
Lyme disease (1 paper, 2021). Lyme disease (named after the towns in the USA where the disease was first identified) is a bacterial infection caused by Borrelia burgdorferi. "Furthermore, HIF-1α pathway activation and increase in glycolysis-derived lactate was also confirmed in Lyme disease patients, which leads to different symptoms and outcome of Lyme disease." (PMID 33912719, 2021).
metastatic colorectal cancer (1 paper, 2021). "A previous clinical study reported that HIF1α was significantly upregulated in bevacizumab resistant metastatic colorectal cancer, thus it is a potential biomarker of anti-angiogenesis resistance." (PMID 34753906, 2021).